BRCA2 (BRCA2 DNA repair associated)
Diseases named in the same sentence as BRCA2 in open-access papers (continued):
Sharing a sentence is not in itself a finding about the gene and the disease.
ovarian tumors (continued). "An example was the discovery of mutations in the BRCA1 and BRCA2 genes which entail a substantial increase in the risk of developing cancers, mainly breast and ovarian neoplasms, often leading to drastic preventive decisions such as prophylactic mastectomy and/or oophorectomy." (PMID 40863452, 2025). "We tested this hypothesis by analyzing a dataset of patients with pathogenic BRCA2-mutant ovarian tumors and found that low APE1 expression in the tumors correlated with worse progression-free survival in BRCA2-mutation carriers." (PMID 41162355, 2025). "In addition, 18 breast or ovarian tumors (18/70, 26%), including the three cases with germline BRCA2 mutations, exhibited a predominant “BRCAness” mutational signature, an indicator of functional BRCA1/BRCA2 deficiency." (PMID 29464067, 2018). "BRCA1 and BRCA2 mutations are associated with a higher risk of breast and ovarian tumors." (PMID 29026449, 2017). "Indeed, ovarian tumors with BRCA1 or BRCA2 mutations, either germline or somatic, are associated with higher mutational burden and better survival outcomes following treatment with platinum-based chemotherapy or PARP inhibitors." (PMID 27959926, 2016). "In BRCA2-mut ovarian tumors, functions included regulation of phosphorylation, vesicle transport, and regulation of signaling." (PMID 40647506, 2025). "The molecular mechanisms that confer this differential clinical profile between BRCA1- and BRCA2-mutant ovarian tumors are not well understood." (PMID 39028933, 2024). "MeSH descriptors and keywords, such as “BRCA1 genes,” “BRCA2 genes”, “Latin America”, and “ovarian neoplasms” were used, along with terms related to socioeconomic and health factors." (PMID 39338246, 2024). "Transcriptomic and pathway analyses comparing BRCA1-mutant, BRCA2-mutant, and homologous recombination wild-type ovarian tumors showed differential regulation of the Wnt/β-catenin pathway." (PMID 39028933, 2024). "In a clinical cohort of human ovarian tumours, low levels of BRCA2 expression with high levels of MRE11 co-expression were linked with worse progression-free survival (PFS) (p = 0.005) and overall survival (OS) (p = 0.001)." (PMID 37446144, 2023). "In this multicentre study, we evaluated the association of ovarian tumour histology with germline BRCA1 and BRCA2 pathogenic variant status." (PMID 37076566, 2023). "To further validate these results, we assessed BRCA2 isoform expression in an independent cohort of 42 BRCA1/2 mutation-associated primary breast and ovarian tumors." (PMID 36344544, 2022). "In 2008, two of the three types of human recurrent ovarian tumors displaying mutations restoring an open reading frame (ORF) function and loss of the mutant BRCA2 allele were reported, and the outcomes were a corrected frameshift of BRCA reading frame." (PMID 36253861, 2022). "Further validation of key results (LOH transitions, PARP1 amplifications, BRCA2 isoform switching) in an independent cohort of paired primary and recurrent BRCA1/2 mutation-associated breast and ovarian tumors will be important." (PMID 36344544, 2022). "First, we examined formalin-fixed, paraffin-embedded (FFPE) tissue samples from the ovarian tumor of the patient by BRCA1/2 all-exon sequencing and found a point mutation (G>T) in the c.7795 position in the exon 16 of the BRCA2 gene." (PMID 34068254, 2021). "The efficiency of PARP inhibitors was first related to pathogenic alterations in BRCA1 and BRCA2, but homologous recombination deficiency (HRD) has since been proven to sensitize ovarian tumors to PARP inhibitors as well." (PMID 34206535, 2021).
ovarian tumors (continued). "Clinical trials with inhibitors such as AZD2281, 6-Mercaptopurine, and methotrexate are ongoing for BRCA2 defective ovarian tumors focused on resistance." (PMID 34065235, 2021). "In this study, LOH was observed in 91 and 67% of ovarian tumors with a BRCA1 and BRCA2 germline pathogenic mutation, respectively, which is in accordance with previous reports." (PMID 32850417, 2020). "Jazaeri and colleagues quantified gene expression for 61 ovarian tumours, which included 18 BRCA1- and 16 BRCA2-associated tumours." (PMID 33081408, 2020). "In an attempt to purify these groups, samples that were misclassified were excluded from further analysis, leaving only 23 familial (13 BRCA1, 10 BRCA2) and 14 sporadic ovarian tumour samples." (PMID 33081408, 2020). "Recently, BRCA1 and BRCA2 somatic mutations were detected in circulating free DNA of breast and ovarian tumors resistant to platinum-based therapy and to PARPi in patients with BRCA1 and BRCA2 germline mutations." (PMID 30669514, 2019). "As a second tumour‐derived model, we used PEO1 cells established from a human ovarian tumour carrying a N‐terminal BRCA2 truncation, which abrogates HR repair." (PMID 31273933, 2019). "Sporadic breast and ovarian tumors show amplification of EMSY, a binding partner of BRCA2, and have been associated with poor survival." (PMID 29459887, 2018). "In the initial ovarian tumor, biallelic BRCA2 inactivation was present, with the known germline p.W563*BRCA2 mutation and a second somatic frameshift p.K650fs*8 deletion detected at an allele frequency of 16.4% (105/639 reads)." (PMID 29262651, 2017). "Analysis of primary data from TCGA identified 100 breast and ovarian tumors with germline BRCA1 (n = 55) and BRCA2 (n = 45) mutations." (PMID 28831036, 2017). "We have performed an in-depth examination of the genomic profiles of primary breast and ovarian tumors in patients with germline BRCA1 and BRCA2 mutations with the goal of identifying correlates of therapeutic response, using two data sets." (PMID 28831036, 2017). "The HR-pathway and expression of BRCA1 and BRCA2 is extremely relevant in ovarian tumors, and we observed that there is detectable expression of miR-1255b, miR-148b*, and miR-193b* in a panel of ovarian tumor lines." (PMID 24843000, 2014). "Five new BRCA1 mutant ovarian tumors and four new BRCA2 mutant ovarian tumors were analyzed compared to the previous studies." (PMID 25437005, 2014). "The best-known hereditary cancer genes, BRCA1 and BRCA2, contribute to substantial share of breast and ovarian tumor incidence around the globe, and have been studied with significant level of comprehension." (PMID 21819606, 2011). "Like BRCA1 and BRCA2, therefore, it appears that LKB1 mutations can cause ovarian tumours when present in the germline, but occur rarely in the soma." (PMID 10389980, 1999). "Interestingly, our analysis of the BRCA2-mutant ovarian tumor dataset revealed that tumors with high APOBEC3 levels (combined A3A and A3B) and low APE1 expression were associated with the worst overall survival compared to all other combinations." (PMID 41162355, 2025). "In this study, we assessed the utility of ovarian tumour characteristics as predictors of BRCA1 and BRCA2 variant pathogenicity, for application using the American College of Medical Genetics and the Association for Molecular Pathology (ACMG/AMP) variant classification system." (PMID 37076566, 2023). "We first tested whether BRCA2 protein expression confirmed the predicted expression by molecularly characterized and sequenced ovarian tumor samples, via IHC." (PMID 36230652, 2022).
ovarian tumors (continued). "It is now well established that cancers that exhibit pathogenic variants in BRCA1 or BRCA2 respond well to treatment with PARPi, a therapeutic strategy that has emerged for BRCA1- and BRCA2-mutated breast and ovarian tumors." (PMID 33195396, 2020). "BRCA genes are also involved in the development of sporadic breast and ovarian tumors; and patients, carrying a germline or somatic BRCA1/BRCA2 variants, may benefit from PARP inhibitors therapy." (PMID 31065452, 2019). "Moreover, we analyzed the differential expression of SORBS2 in (a) BRCA1 mutant and BRCA2 mutant tumor tissues compared with wild-type tumor tissues; (b) CCNE1high and CCNE1low ovarian tumor tissues in TCGA dataset." (PMID 29548303, 2018). "HRD-Mean scores were not significantly different between BRCA1 and BRCA2 germline mutation-associated breast and ovarian tumors." (PMID 28831036, 2017). "Either genetic or somatic mutations of BRCA1 and BRCA2 are found in approximately 20% of all ovarian tumors; when considering all kinds of BRCA1/2 alterations, including mutations, these have been reported in up to 82% of ovarian tumors." (PMID 25136623, 2014). "In aggregate, our findings from the largest single study of breast and ovarian tumors associated with BRCA1 and BRCA2 germline mutations suggest that locus-specific LOH may be a biomarker for a BRCAness phenotype in whole tumor formalin-fixed paraffin embedded (FFPE) specimens." (PMID 28831036, 2017). "Both BRCA1 and BRCA2 germline mutation-associated breast and ovarian tumors had a significantly lower proportion of the aging signature (Signatures 1 and 5) compared to nonBRCA breast and ovarian tumors." (PMID 28831036, 2017). "Despite the observed associations between BRCA1 and BRCA2 germline pathogenic variant status with ovarian tumour characteristics, currently VUS interpretation efforts do not consider ovarian tumour pathology." (PMID 37076566, 2023). "The distribution of ovarian tumour characteristics differs between germline BRCA1 and BRCA2 pathogenic variant carriers and non-carriers." (PMID 37076566, 2023). "Moreover, a recent work showed that EZH2 expression predicts outcome in patients with BRCA2-mutant ovarian tumors by regulating genomic stability at stalled replication forks, suggesting a possible connection between EZH2 and BRCA2." (PMID 34573332, 2021). "In contrast, BRCA2 inactivation does not occur by promoter hypermethylation—a significant number of sporadic breast and ovarian tumors show amplification of EMSY at the gene level." (PMID 29459887, 2018). "We found that both BRCA1 and BRCA2 ovarian tumors without locus-specific LOH treated with adjuvant platinum based chemotherapy have lower overall survival than tumors with locus-specific LOH, at rates similar to sporadic tumors." (PMID 28831036, 2017). "For the evaluation of our approach, 127 ovarian tumor samples derived from 96 patients were tested: 29 with a BRCA1, 14 with a BRCA2, and 53 without a germline mutation in either gene." (PMID 27767231, 2017). "Three of 23 (13%) breast and three of 15 (20%) ovarian tumors associated with BRCA1 germline mutations, and seven of 16 (44%) breast and one of six (17%) ovarian tumors associated with BRCA2 germline mutations did not have BRCA locus-specific LOH." (PMID 28831036, 2017). "We determined whether combined BRCA2 and PARP1 inhibition could prevent or delay growth of ovarian tumors in vivo." (PMID 26959114, 2016). "In addition to the predictive significance of BRCA2/FEN1 co-expression, the data also suggests that a proportion of ovarian tumors with low BRCA2 may also overexpress FEN1." (PMID 33919707, 2021). "No genes were differentially expressed between BRCA2-mutated and non-BRCA-mutated ovarian tumours." (PMID 33081408, 2020).
ovarian tumors (continued). "In this study, individual ovarian tumor cells revealed the heterogeneity involved in resistance mechanisms, rewiring the HRR pathway, regaining replication fork capacity and protection, and the upregulation of drug efflux pump MDR genes independent of BRCA1/BRCA2 levels." (PMID 36253861, 2022).
gastric cancer (62 papers, 2002 to 2026). A primary or metastatic malignant neoplasm involving the stomach. "Over the years, growing evidence has supported an increased gastric cancer risk associated with BRCA2 PVs." (PMID 40649708, 2025). "Ultimately, a better understanding of gastric carcinogenesis in BRCA1 and BRCA2 carriers will have important implications for gastric cancer risk management amongst this high-risk cohort." (PMID 41256354, 2025). "An accumulating body of evidence suggests carriers of a pathogenic germline variant (PGV) in BRCA1 or BRCA2 have increased gastric cancer (GC) risk." (PMID 41256354, 2025). "Although BRCA2 germline mutation (p.Y1894*) was detected in blood and all three tumors, a new BRCA2 somatic mutation (p.S744X) was detected in gastric cancer." (PMID 35912179, 2022). "In recent years, a retrospective multicenter data analysis of gastric cancer with BRCA1 or BRCA2 germline mutations (gBRCAm) was conducted to identify 10 gastric cancer patients with gBRACm, 6 of whom had metastatic disease." (PMID 36035159, 2022). "Herein, we review the accumulating evidence that suggests BRCA1/2 carriers are at increased risk for gastric cancer, particularly among BRCA2 carriers." (PMID 36497436, 2022). "BRCA2 mutation increases oesophageal and gastric cancers based on two and six studies, respectively." (PMID 34577828, 2021). "Data on family history and PrC outcomes in BRCA2 mutation carriers show an increased number of multiple PrC and stomach cancers and a worse prognosis, as compared with previously published results." (PMID 33710808, 2021). "The association between pathogenic mutations in BRCA1 and BRCA2 and other gastrointestinal tumors such as colorectal, gastric cancers, cholangiocarcinoma and hepatocellular carcinoma is unclear." (PMID 33198203, 2020). "BRCA1/2 are tumor suppressors involved in pathways important for regulating DNA damage, and BRCA2 mutations were found to be associated with familial aggregations of not only breast but also of stomach cancers." (PMID 30866995, 2019). "The results of this study corroborated the concept that stomach cancer is part of the spectrum of diseases associated with BRCA2 mutations." (PMID 26779294, 2016). "The correlation between BRCA2 gene mutations and gastric cancer was investigated in direct mutational analysis in an Israeli group." (PMID 26779294, 2016). "They estimated that in Jewish individuals germline mutations in BRCA2 seem to contribute to the genetic susceptibility toward gastric cancer." (PMID 26779294, 2016). "The findings from this previous study showed that in the occurrence of breast and stomach cancer among first-degree relatives, BRCA2 mutations were detected in 16.7 %." (PMID 26236408, 2015). "The relative risk of stomach cancer was significantly increased among the BRCA2 mutation positive cohort and was reported to be 2.40-fold for first-degree relatives and 1.91-fold for second-degree relatives." (PMID 26236408, 2015). "Findings from the Jakubowska study suggest the presence of a germline BRCA2 mutation among these families given the incidence of ovarian and stomach cancer among families in the Polish population." (PMID 26236408, 2015). "In an earlier study it was reported that male stomach cancer was over-represented in BRCA2 mutation positive families." (PMID 12373604, 2002). "Recently, it has been reported that the incidence of stomach cancer is significantly increased in BRCA2 gene mutation carriers." (PMID 12373604, 2002). "It has also been shown that the frequency of the BRCA2 6174delT mutation among consecutive Jewish patients with stomach cancer is 5.7%, which is approximately five times higher than in the general population." (PMID 12373604, 2002).